FBXW7 (F-box and WD repeat domain containing 7)
Diseases named in the same sentence as FBXW7 in open-access papers (continued):
Sharing a sentence is not in itself a finding about the gene and the disease.
pancreatic cancer (continued). "SINE KPT-185, an inhibitor of exportin 1, blocks the nuclear export of FBXW7 and thereby promotes degradation of Notch1 in the nucleus of pancreatic cancer cells." (PMID 32429232, 2020). "Genistein down-regulates expression of the microRNA miR-223, resulting in up-regulation of FBXW7 expression, inhibition of cell growth and invasion, and induction of apoptosis in pancreatic cancer cells." (PMID 32429232, 2020). "Further, in pancreatic cancer (PC), it has also been demonstrated that upregulation of FBXW7 substantially enhanced the chemosensitivity of the PC cells to gemcitabine via increased expression of equilibrative nucleoside transporter 1 (ENT1)." (PMID 30791487, 2019). "In vitro silencing of FBXW7 significantly enhanced pancreatic cancer (PC) cell proliferation, migration, and invasion and rendered resistance to gemcitabine and nab-paclitaxel due to the accumulation of MCL1." (PMID 30791487, 2019). "Some WDR proteins are also known to regulate metabolic pathways in cells, for example, F-box and WD Repeat Domain-Containing 7 (FBW7) protein negatively regulates glucose metabolism in pancreatic cancer." (PMID 29896207, 2018). "In this study, we investigated the function and clinical significance of FBXW7 in pancreatic cancer." (PMID 29348852, 2017). "FBXW7 expression was immunohistochemically evaluated in 122 pancreatic cancer tissues and was found to be mainly expressed in the nucleus." (PMID 29348852, 2017). "In the present study, we examined FBXW7 expression in 122 pancreatic cancer tissues using immunohistochemistry to clarify the clinical significance of FBXW7 expression." (PMID 29348852, 2017). "Knockdown of FBXW7 in vitro enhanced cell proliferation, and migration, and invasion abilities and promoted gemcitabine and nab-paclitaxel chemoresistance in pancreatic cancer cells." (PMID 29348852, 2017). "We next evaluated the effects of FBXW7 knockdown on resistance to gemcitabine and nab-paclitaxel, which are used in first-line chemotherapy regimens for patients with advanced pancreatic cancer." (PMID 29348852, 2017). "In our in vitro analysis, we found that knockdown of FBXW7 enhanced cell proliferation, migration, and invasion abilities, and decreased sensitivity to gemcitabine and nab-paclitaxel in pancreatic cancer cells." (PMID 29348852, 2017). "Accordingly, the aim of this study was to identify the function and clinical significance of FBXW7 in pancreatic cancer." (PMID 29348852, 2017). "This low FBXW7 protein expression results in accumulation of multiple FBXW7 substrates in pancreatic cancer." (PMID 29348852, 2017). "However, conditional deletion of Fbxw7 accelerates KrasG12D driven pancreatic cancer in a genetically engineered mouse model." (PMID 31748650, 2019). "Furthermore, FBXW7 is significantly co-mutated with KRAS in colon cancer and ATM is significantly co-mutated with KRAS in pancreatic cancer." (PMID 31748650, 2019). "Interestingly, EZH2 has been reported to be a substrate of FBXW7 in pancreatic cancer cells and is negatively correlated with FBXW7 expression in human pancreatic cancer samples." (PMID 30086763, 2018). "In addition, reduced FBXW7 expression enhanced tumor cell proliferation, migration, and invasion and the sensitivity of pancreatic cancer cells to gemcitabine and nab-paclitaxel was regulated by FBXW7 via MCL1 accumulation." (PMID 29348852, 2017). "Moreover, a recent study showed that β-catenin, which regulates the Wnt signaling pathway and is related to pancreatic cancer malignancy, is a target of FBXW7." (PMID 29348852, 2017). "FBXW7 expression was evaluated by immunohistochemistry in 122 pancreatic cancer tissues." (PMID 29348852, 2017). "Furthermore, we demonstrated MCL1 is a key substrate of FBXW7 involved in chemotherapeutic resistance in pancreatic cancer." (PMID 29348852, 2017). "FBXW7 protein was expressed in SUIT-2 pancreatic cancer cells." (PMID 29348852, 2017).
pancreatic cancer (continued). "Treatment of cultured pancreatic cancer cells with genistein downregulated the expression of miR-223 and miR-34a which increased the levels of their target proteins F-box and WD repeat domain-containing 7 (Fbw7) and Notch-1 and reduced growth." (PMID 28955205, 2017). "In conclusion, we found that FBXW7 expression levels in primary tumor tissues could predict prognosis in patients with pancreatic cancer." (PMID 29348852, 2017). "Moreover, although the mechanisms regulating FBXW7 expression are gradually being elucidated, studies on the impact of FBXW7 expression and its substrate in pancreatic cancer are limited." (PMID 29348852, 2017). "In addition, FBXW7 can regulate apoptosis and ferroptosis in pancreatic cancer cells." (PMID 35280682, 2022). "In addition, ERK phosphorylates and destabilizes FBXW7 in pancreatic cancer." (PMID 33494392, 2021). "Thus, FBXW7 expression in pancreatic cancer may be a promising prognostic marker, consistent with previous reports in other cancers." (PMID 29348852, 2017). "Thus, the FBXW7/MCL1 axis may be a promising therapeutic tool to overcome refractory pancreatic cancer." (PMID 29348852, 2017). "Moreover, the effects of FBXW7 downregulation by RNA interference (RNAi) were examined in pancreatic cancer cells to evaluate whether FBXW7 played important roles in proliferation, migration, invasion, and chemoresistance." (PMID 29348852, 2017). "Thus, FBXW7 expression status in cancer tissue may be a predictive marker of standard chemotherapy for pancreatic cancer." (PMID 29348852, 2017). "In the preliminary research, we found that F-box and WD repeat domain-containing 7 (FBW7) inhibited the migration and proliferation of pancreatic cancer cells through its substrate c-Myc." (PMID 39827156, 2025). "Enhancer of zeste homolog 2 (EZH2), a substrate of FBXW7, figures as an oncogenic protein facilitating invasion and metastasis of pancreatic cancer cells, which can be abrogated by CDK5/FBXW7-dependent degradation." (PMID 35515121, 2022). "PRMT5 epigenetically regulated the expression of FBXW7, contributing to elevated c-MYC levels and subsequently enhanced glycolysis and proliferation of pancreatic cancer cells." (PMID 35515121, 2022). "F-Box and WD repeat domain containing 7 (FBXW7), a tumor-suppressive E3 ligase, is known to degrade SHOC2 leucine-rich repeat scaffold protein (SHOC2), which activates Ras/ERK signaling in pancreatic cancer." (PMID 33066509, 2020). "MCL1, which is a target of FBXW7 and a member of the BCL2 protein family, is an anti-apoptotic protein that has been reported to be overexpressed in pancreatic cancer cells and clinical tissue samples and is correlated with advanced disease." (PMID 29348852, 2017). "Recently, Jin and colleagues demonstrated that FBXW7 suppresses enhancer of zeste homolog 2 (EZH2) activity and inhibits tumor migration and invasion via degradation of EZH2 in pancreatic cancer cells." (PMID 29348852, 2017). "However, only miR-103 was directly involved in the regulation of pancreatic cancer-associated processes: E-cadherin signalling events (CDH1), TGF beta signalling pathway (TGFBR2, APC, CDH1, CREBBP, EP300, SMAD3, TSC2), and altered TFG-beta SMAD dependent signalling (TGFBR2, SMAD3, and FBXW7)." (PMID 29285254, 2017). "Additionally, PRMT5 can suppress the E3 ubiquitin ligase FBXW7 (F-box and WD-40 domain-containing protein 7, also known as FBW7) in pancreatic cancer." (PMID 39594744, 2024). "F-box and WD repeat domain-containing 7 (FBW7), a novel E3 ligase of EZH2, can mediate the phosphorylation, ubiquitination, and degradation of EZH2 with the involvement of the activated CDK5 kinase in pancreatic cancer." (PMID 32723346, 2020).
pancreatic cancer (continued). "Thus, since FBXW7 mediates diverse proteins that regulate malignant potential, such as tumor proliferation, migration, and invasion, which are important for pancreatic cancer progression, FBXW7 induction may be a novel therapeutic strategy to suppress pancreatic cancer development and progression." (PMID 29348852, 2017). "Therefore, it is important to investigate the role of FBXW7 expression, which regulates MCL1, in pancreatic cancer." (PMID 29348852, 2017). "Genetic alterations in tumor suppressor genes found in lower frequency (<10%) in pancreatic cancer include STK11/LKB1, MKK4, TGFβ R1 (ALK 5, chromosome 9q), TGFβ R2 (chromosome 3p), ACVR1β (ALK 4, chromosome 12q), ACVR2 (chromosome 2q), FBXW7 (CDC4), EP300, BRCA2, ATM, and AKT2." (PMID 24624093, 2014). "Moreover, F-box and WD repeat domain containing 7 (FBW7) inhibits SCD expression through the suppression of nuclear receptor 4 subfamily A group 1 (NR4A1), concurrently regulating apoptosis and ferroptosis in human pancreatic cancer cells (PANC1 and SW1990)." (PMID 38844964, 2024). "In pancreatic cancer, deletion of SETD2 leads to decreased expression of FBXW7, increasing the accumulation of MYC, an FBXW7 substrate, without significantly altering other FBXW7 substrates, such as mTOR and Cyclin E." (PMID 36998461, 2023).
glioma (53 papers, 2007 to 2025). A benign or malignant brain and spinal cord tumor that arises from glial cells (astrocytes, oligodendrocytes, ependymal cells). "Exons 3–4 of FBXW7 encoded 185aa, which inhibited glioma cell proliferation and cell cycle acceleration." (PMID 39519039, 2024). "The tumor growth and metastasis of TNBC and glioma are inhibited by circFBXW7, which encodes protein FBXW7-185aa and blocks miR-197-3p." (PMID 36052282, 2022). "For example, circ-FBXW7 encodes a novel 21 kDa protein called FBXW7-185aa in glioma, which inhibits proliferation and cell cycle acceleration." (PMID 32894165, 2020). "Circ-FBXW7 encodes FBXW7-185aa, which can shorten the half-life of c-Myc and slow the proliferation of glioma cells." (PMID 30736838, 2019). "Further, knock-down of FBXW7 amplified the expression of cell cycle proteins including cyclin A2 and cyclin E2 in basic condition and miR-10b deficient glioma cells, affirming its role as a regulator of cell cycle proteins’ degradation." (PMID 30791487, 2019). "We suggest that loss of FBXW7 plays an important role in glioma malignancy by allowing the accumulation of multiple oncoproteins and that interfering with Fbxw7 or its downstream targets would constitute a new therapeutic advance." (PMID 17326833, 2007). "Furthermore, FBXW7 overexpression is involved in proliferation inhibition of glioma cells, while its deletion causes instability in chromosome segregation during mitosis, a process controlled by several SCFFbxw7 targets, including Aurora-A." (PMID 33665742, 2021). "In addition, circ-SHPRH and circ-FBXW7 and their encoded proteins are highly expressed in normal brains but downregulated in gliomas." (PMID 33627631, 2021). "FBXW7 is mutated in different cancer cell lines and human tumors, including gliomas." (PMID 33665742, 2021). "Recently, it was reported that circular RNA form of the FBXW7 (circ-FBXW7) and its encoded protein FBXW7–185 aa could suppress glioma cell proliferation by arresting cell cycle." (PMID 31519156, 2019). "These proteins play pivotal roles in cellular functions; for example, circ‐SHPRH generates a tumor‐suppressive protein (SHPRH‐146aa), while circ‐FBXW7 produces FBXW7‐185aa, which suppresses glioma tumorigenesis." (PMID 40965819, 2025). "used qRT-PCR in RNA isolated from human glioma biopsies and found that the FBXW7 expression was significantly reduced in GBM tissues compared to normal healthy brain tissues." (PMID 37752997, 2023). "Downregulated Fbxw7 activates Notch pathway in glioma stem cells to suppress immune response by regulating the expression of immune‐associated molecules." (PMID 36971192, 2023). "Recently, clinical tissues and TCGA (The Cancer Genome Atlas) database analysis revealed that FBXW7 expression was inversely correlated with glioma histology and positively with patient survival time." (PMID 35559231, 2022). "Glioma proliferation is significantly impaired when FBXW7 is overexpressed in vitro, suggesting its tumor suppressive role in astroglial cells." (PMID 35559231, 2022). "These circRNAs have open reading frames that encode functional proteins with the help of internal ribosome entry sites, and their corresponding proteins SHPRH-146aa and FBXW7-185aa can inhibit the proliferation of glioma cells." (PMID 33627631, 2021). "For instance, overexpression of circ-FBXW7 that encodes a novel 21 kDa protein composed of 185 amino acids, named F-Box and WD Repeat Domain Containing 7 (FBXW7), repressed cellular proliferation and glioma tumorigenesis." (PMID 32660590, 2020). "It had reported Circ-FBXW7 was decreased in glioma tissues cells, and the overexpression of Circ-FBXW7 would help inhibit cancer cells cycle by regulating the encoding of a proteins, FBXW7-185aa." (PMID 31895689, 2019).
glioma (continued). "A number of circular RNAs (circRNAs) have been identified in various cancer including F-box and WD repeat domain containing 7 (FBXW7) circular RNA (circ-FBXW7), which can suppress glioma cell growth." (PMID 31519156, 2019). "Previous studies have shown that circRNA cZNF292 participates in human glioma tube formation; hsa_circ_0046701 promotes glioma carcinogenesis through the miR-142-3p target ITGB8, and circRNA FBXW7 inhibits glioma tumorigenesis." (PMID 30470262, 2018). "As it encodes an F-box protein that is part of the ubiquitin protein ligase complex, FBXW7 has many known glioma-relevant client proteins including cyclin E, c-Myc, Aurora-A, Notch, and c-Jun." (PMID 18394558, 2008). "We tested the expression of FBXW7 in human glioma biopsies by quantitative PCR and compared the transcript levels of grade IV glioma (glioblastoma, G-IV) with those of grade II tumors (G-II)." (PMID 17326833, 2007). "Proliferation is significantly impaired in glioma cells overexpressing nuclear FBXW7 in vitro suggesting that it acts as a tumor suppressor in astroglial cells." (PMID 17326833, 2007). "In the quest for novel molecular mediators of glioma progression, we studied the regulation of FBXW7 (hCDC4/hAGO/SEL10), its association with survival of patients with glioblastoma and its potential role as a tumor suppressor gene in glioma cells." (PMID 17326833, 2007). "The expression levels of FBXW7 in most malignancies are downregulated compared to normal tissues, such as glioma, lung cancer, liver cancer, urothelial cancer, ovarian cancer, and melanoma, which have a positive correlation with prognosis of patients, aside from liver cancer and melanoma." (PMID 35515121, 2022). "Although circRNAs belong to non-coding RNAs, recent studies unraveled that circRNAs can be translated into proteins or peptides—for example, circ-FBXW7 encodes a novel 21-kDa protein, called FBXW7-185aa, and the depletion of FBXW7-185aa promotes malignant phenotypes in glioma." (PMID 36338714, 2022). "Moreover, MALAT1 plays a tumor-suppressive role in glioma cells by sponging miR-155, which leads to F-box/WD repeat-containing protein 7 (FBXW7) expression, and its downregulation in glioma tissues is associated with poor survival." (PMID 34202078, 2021). "For example, circ-FBXW7 is downregulated in glioma and a cross‐linked ORF in circ-FBXW7, which is formed by the covalent connection of exon 3 and exon 4 of the FBXW7 gene, encodes a novel 21-kDa protein called FBXW7-185aa in an IRES-driven manner." (PMID 34745938, 2021). "The most significantly mutated genes include FBXW7 (encoding WNT signaling molecule) in B-cell lymphoma, SATB1 (functioning in chromatin remodeling) in T-cell lymphoma, and CALD1 (encoding an actin and myosin binding protein) in glioma." (PMID 34344882, 2021). "For example, MALAT1 promotes FBXW7 expression by acting as ceRNA for miR-155 in glioma cells." (PMID 31248165, 2019). "MALAT1 also promotes FBXW7 expression by acting as a sponge of miR-155 in glioma cells." (PMID 31248165, 2019). "Recently, studies have indicated that FBXW7 circular RNA, circ-FBXW7 has the potential to repress tumorigenesis in brain cancer and may serve as a prognostic marker for glioma." (PMID 30791487, 2019). "FBXW7 is identified as a genuine target of miR-155 in glioma cells." (PMID 30086763, 2018). "Examination of FBXW7 protein expression by immunostaining shows that compared with normal primary tissues, FBXW7 protein expression is greatly reduced in carcinoid, glioma, liver, lung, melanoma, pancreatic, prostate, renal, skin, testis, thyroid and urothelial cancers." (PMID 30086763, 2018). "Next, we investigated the effects of FBXW7 misregulation in glioma cells." (PMID 17326833, 2007). "Finally we show that knocking down FBXW7 in cultured glioma cells destabilizes chromosome segregation at mitosis, a process controlled by several targets of SCFFbxw7 including Aurora-A." (PMID 17326833, 2007).